PTPRT (protein tyrosine phosphatase receptor type T)
Diseases named in the same sentence as PTPRT in open-access papers (continued):
Sharing a sentence is not in itself a finding about the gene and the disease.
colon cancer (5 papers, 2011 to 2021). "Using Apc+/min mouse model, we demonstrate here that knockout of PTPRT increases the size of colon tumors, suggesting that loss of PTPRT promotes tumor progression." (PMID 27447856, 2017). "This notion is further supported by the study showing that PTPRT knockout mice are susceptible to azoxymethane (AOM)-induced colon tumor formation." (PMID 27447856, 2017). "Here, we demonstrated that PTPRT knockout increases the size of colon tumors in Apc+/min genetic background, suggesting that loss of PTPRT promotes tumor progression." (PMID 27447856, 2017). "RELN and ALDH1A1 are expressed in prostate cancer, ENG, SI, FCGBP and PTPRT are associated with colonic tumors." (PMID 21533145, 2011). "Their functional relevance is demonstrated by the fact that ectopic PTPRD expression induces apoptosis in cancer cells and inhibits their oncogenic, metastatic properties, and PTPRT knockout mice are highly sensitive to carcinogen-induced colon cancer." (PMID 30200630, 2018). "Here we report that PTPRT knockout increases the size of mouse colon tumors in the Apcmin+/− genetic background, suggesting that inactivation of PTPRT promotes tumor progression." (PMID 27447856, 2017). "Given that PTPRT dephosphorylates paxillin at Y88 residue, we performed immunohistochemistry staining of colon tumors harvested from the mice." (PMID 27447856, 2017). "Consistent with our previous observation, knockout of PTPRT leads to increased levels of pY88 paxillin in colon tumors." (PMID 27447856, 2017). "Although compelling evidence has put forward PTPRT as a colon cancer susceptibility gene, thus far no reports have linked PTPRT to gliomas." (PMID 27586084, 2016).
head and neck squamous cell carcinoma (5 papers, 2015 to 2024). A squamous cell carcinoma that arises from any of the following anatomic sites: lip and oral cavity, nasal cavity, paranasal sinuses, pharynx, larynx, and salivary glands. "PTPRT with a mutation (A1022E) in the catalytic domain resulted in increased phosphorylation of STAT3 in head and neck squamous cell carcinoma (HNSCC) cells." (PMID 29558404, 2018). "A follow-up mutational analysis of PTP family genes in head and neck squamous cell carcinomas (HNSCC) also found that PTPRT is frequently mutated in this tumor type." (PMID 27447856, 2017). "A recent head and neck cancer study confirmed that mutation of PTPRT results in increased phosphor-STAT3 levels in the head and neck squamous cell carcinoma tumors." (PMID 25970784, 2015). "We recently reported the cumulative mutation profile of the PTPR gene family in cancer with a focus on PTPRT mutation leading to STAT3 activation in head and neck squamous cell carcinoma (HNSCC)." (PMID 26267899, 2015). "Several evidences suggested that PTPRT functions as a tumor suppressor in human cancers including colorectal cancer, head and neck squamous cell carcinoma, and retinoblastoma." (PMID 29558404, 2018).
Obesity (5 papers, 2014 to 2021). Accumulation of substantial excess body fat. "So far, PTPRT was shown to cause obesity with altered insulin resistance and lowered feed intake in a knock-out mouse model, whereas in cattle, it was associated with meat quality traits." (PMID 31316547, 2019). "Consistent with this notion, several recent human genetic studies linked obesity to chromosome 20q12–13, the genomic region in which PTPRT is located." (PMID 24949727, 2014). "To elucidate the molecular mechanisms by which Ptprt−/− mice resist high-fat diet-induced obesity, we assessed PTPRT expression in tissues implicated in metabolic regulation." (PMID 24949727, 2014). "PTPRT (protein tyrosine phosphatase receptor type T) has been reported to serve a role in obesity associated insulin resistance, but this gene might be involved in progression of T1D." (PMID 33827531, 2021). "In humans, PTPRT is strongly associated with high-fat diet-induced obesity and insulin resistance." (PMID 27589727, 2016). "Protein tyrosine phosphatase receptor type T is known to prevent obesity by regulating the metabolism in high-fat-diet mice, and metabolic imbalances reduce the expression of proto-oncogene protein WNT3 in obese and diabetic samples." (PMID 34561612, 2021). "As such, the decrease in NPY in Ptprt−/− mice further suggests the role of PTPRT in nervous system regulating obesity and peripheral insulin resistance." (PMID 24949727, 2014). "Here, we report that protein tyrosine phosphatase receptor T (PTPRT) knockout mice are resistant to high-fat diet-induced obesity." (PMID 24949727, 2014). "Because we previously showed that STAT3 is a substrate of protein tyrosine phosphatase receptor T (PTPRT), we investigate here whether PTPRT regulates food intake and obesity in mice." (PMID 24949727, 2014). "Our data suggest that PTPRT could be a drug target for obesity, because Ptprt−/− mice resist many key effects of a high-fat diet, including increased body mass, hyperglycemia, hypercholesterolemia, insulin resistance and increased adiposity." (PMID 24949727, 2014).
head and neck cancer (4 papers, 2015 to 2022). A primary or metastatic malignant neoplasm affecting the head and neck. "This is similar to a recent report for PTPRT in Head and Neck cancer and suggests a tumor suppressor type role." (PMID 36054194, 2022).
Insulin resistance (4 papers, 2014 to 2021). Increased resistance towards insulin, that is, diminished effectiveness of insulin in reducing blood glucose levels. "Taken together, our data suggest that loss of PTPRT function attenuates the development of peripheral insulin resistance after a high-fat diet." (PMID 24949727, 2014).
Intellectual disability (4 papers, 2017 to 2023). "Notably, an individual with intellectual disability and a de novo PTPRT variant has previously been reported." (PMID 37056996, 2023). "PTPRT gene abnormalities induce neurological diseases such as intellectual disability, autism, and depression." (PMID 34815513, 2021).
metastatic colorectal cancer (4 papers, 2021 to 2023). "A study demonstrated that PTPRT may predict bevacizumab chemotherapy resistance with deleterious mutation of PTPRT causing a poor prognosis in metastatic colorectal cancer." (PMID 34862763, 2022). "Deleterious mutations or copy number loss of PTPRT and its related gene PTPRD are potential markers for evaluating resistance to bevacizumab regimens and are closely associated with shorter PFS in metastatic colorectal cancer patients." (PMID 37158817, 2023).
non-small cell lung carcinoma (4 papers, 2019 to 2025). A group of at least three distinct histological types of lung cancer, including non-small cell squamous cell carcinoma, adenocarcinoma, and large cell carcinoma. "In a recent investigation, the authors used mass spectrometry, Western blot, immunofluorescent staining, and next-generation sequencing (NGS) to investigate the response of PTPRT-deficient non-small-cell lung cancer to anti-PD-1therapy." (PMID 40149335, 2025). "A combined analysis using a dataset from the genomics evidence neoplasia information exchange (GENIE) and cBioPortal revealed that PTPRT mutation is associated with poor prognosis in pan-cancer and non-small-cell lung cancer." (PMID 35789644, 2022). "Gene expression data of non-small cell lung cancer (NSCLC) samples from The Cancer Genome Atlas database were downloaded and used to detect the differential expressed genes between PTPRT-high and PTPRT-low subgroups." (PMID 38216925, 2024).
autism (3 papers, 2017 to 2021). Persistent deficits in social interaction and communication and interaction as well as a markedly restricted repertoire of activity and interest as well as repetitive patterns of behavior. "In humans, PTPRT has been associated with autism, which is comorbid with DMD." (PMID 29554127, 2018).
gastric cancer (3 papers, 2022 to 2025). A primary or metastatic malignant neoplasm involving the stomach. "Among the Fujian cohort mutations classified as metastatic markers in gastric carcinomas, one is a PTPRT mutation, and another, Chondrosarcoma TERT promoter mutation is a metastasis marker." (PMID 40758706, 2025).
leukemia (3 papers, 2019 to 2022). A malignant (clonal) hematologic disorder, involving hematopoietic stem cells and characterized by the presence of primitive or atypical myeloid or lymphoid cells in the bone marrow and the blood. "Other miR-139 targets that are described in leukemia and some other types of cancer are BTG3, the RNA-binding protein ELAVL1, Tetraspanin-3 (TSPAN3), MAX Network Transcriptional Repressor (MNT), 15-Hydroxyprostaglandin Dehydrogenase (HPGD) and Protein Tyrosine phosphatase Receptor Type-T (PTPRT)." (PMID 35269391, 2022). "All mice reconstituted with PTPRT−/− HCK-over-expressing HSPCs revealed hyperphosphorylation of STAT3 but the precise copy numbers of HCK were not ascertained and it is possible that there is a gene dosage effect that is necessary to establish a MPN/leukemia phenotype." (PMID 31065022, 2019).
metastatic disease (3 papers, 2018 to 2022). "On the other hand, clonal mutations in ARNT (OVA_047), NTRK1 (OVA_048), MYH9 (OVA_047) and PPARG (OVA_047), and subclonal mutations in ITGAV (OVA_047) and PTPRT (OVA_003) were all specific to metastatic tumours." (PMID 32099096, 2020). "It is necessary to underline that although mutated ERBB2, PTPRT, PTPRD and AURKB predicted poor OS in univariate analysis they were excluded from the multivariate analysis because they were preferentially identified in patients with late stage (stage III-IV) and/or metastatic disease." (PMID 29844865, 2018).
Anxiety (2 papers, 2017 to 2022). Intense feelings of nervousness, tension, or panic often arise in response to interpersonal stresses. "They observed only a slight change in locomotor activities and anxiety-related behaviors in the homozygous knocking mice with PTPRT mutation, and higher social approach scores in male homozygous mice." (PMID 28796977, 2017). "We further looked into our molecular data, including ventral hippocampal gene expression of two genes: Ptprt, (encoding protein tyrosine phosphatase receptor type T), involved in the development of dendrite spines; and Htr2b (encoding serotonin receptor 2b), important for anxiety-related behavior." (PMID 36307876, 2022).
glioblastoma (2 papers, 2016 to 2018). The most malignant astrocytic tumor (WHO grade IV). "To also monitor potential DUSP26 or PTPRT effects on glioblastoma cell migration, we turned to a previously established spheroid outgrowth assay." (PMID 27586084, 2016). "PTPRT mRNA levels are quite low in normal brain tissue and lower grade gliomas but are still on average 40-fold higher than those in high grade glioblastomas." (PMID 27586084, 2016). "In line with a tumor suppressive role, we found that PTPRT overexpression significantly suppressed glioblastoma cell proliferation and migration." (PMID 27586084, 2016). "Three of these genes (PTPRZ1, PTEN, PTPRT) encode PTPs with C-terminal PDZ binding motifs and mapping of the interacting PDZ domain-containing proteins may be of relevance for glioblastoma etiology." (PMID 29439552, 2018). "DUSP26 and PTPRT thus impinge on both growth and motility of glioblastoma cells." (PMID 27586084, 2016). "Importantly, overexpression of the two PTPs that showed the largest expression difference in our qPCR and in silico analyses, DUSP26 and PTPRT, resulted in reduced glioblastoma cell proliferation and migration, supportive of a tumor suppressive role." (PMID 27586084, 2016). "In addition, for the PDZ target sequence (“SSF”;) in the glioblastoma-relevant PTPRT knowledge on the glioblastoma PDZ interactome could provide new therapeutic avenues." (PMID 29439552, 2018). "Tumor-relevant levels of 2-HG were added for 48 h to U-251 MG (IDH1 wild type) glioblastoma cells and potential changes in DUSP16, PTPRG and PTPRT expression levels were monitored." (PMID 27586084, 2016). "For DUSP26, PTEN, PTPRM and PTPRT, lower expression levels correlated with poor prognosis, and overexpression of DUSP26 or PTPRT in E98 glioblastoma cells reduced tumorigenicity." (PMID 27586084, 2016). "Notably, seven PTP genes (DUSP26, MTMR4, PTEN, PTPRM, PTPRN2, PTPRT and PTPRZ1) were differentially expressed between grade II-III gliomas and (grade IV) glioblastomas." (PMID 27586084, 2016). "Also within the individual histological types (oligodendroglioma (grade II-III), astrocytoma (grade II-III) and glioblastoma (grade IV)) we observed expression-dependent survival probabilities for DUSP26 and PTPRT (data not shown)." (PMID 27586084, 2016).
glioma (2 papers, 2016 to 2021). A benign or malignant brain and spinal cord tumor that arises from glial cells (astrocytes, oligodendrocytes, ependymal cells). "DUSP26 and PTPRT are the most down-regulated PTPs in gliomas with highest grade malignancy and both show a pronounced correlation with survival probability." (PMID 27586084, 2016). "We additionally identified PTPRT, DUSP26, PTPRN2 and MTMR4 in our screen for glioma-relevant PTPs." (PMID 27586084, 2016). "RNAseq data from WT or IDH1 R132H-containing glioma xenografts E434 and E478 also do not point to an IDH-mutation associated difference in expression for DUSP16, PTPRG and PTPRT (WPJL, unpublished data)." (PMID 27586084, 2016). "The finding that the closely related PTPRT and PTPRM show distinct expression patterns in lower versus high grade gliomas (PTPRU just failed to reach the criteria in the first cohort) and correlate with patient survival, warrants further studies on their role in glioma-associated signaling pathways." (PMID 27586084, 2016).
hepatocellular carcinoma (2 papers, 2020 to 2021). A malignant tumor that arises from hepatocytes. "miR-532-3p promotes hepatocellular carcinoma progression by targeting PTPRT." (PMID 33231561, 2020).
metastatic cancers (2 papers, 2019 to 2022). A carcinoma which has spread from the original site of growth to another anatomic site. "The mutations of PTPRT or “gene modules” containing PTPRT are significantly enriched in patients with metastatic cancer in multiple cancers, suggesting that the PTPRT mutations serve as potential biomarkers of cancer metastasis." (PMID 35789644, 2022). "Additionally, many gene modules involved in PTPRT were significantly enriched in metastatic cancers." (PMID 35789644, 2022).
parasitic infections (2 papers, 2020 to 2024). "In production animals, a relationship between the PTPRT gene polymorphisms and resistance to some bacterial and parasitic infections was observed, such as resistance to brucellosis in goats and tuberculosis in cattle." (PMID 38902640, 2024). "In farm animals,a connection between the PTPRT gene polymorphism andresistance to some bacterial and parasitic infections was revealed." (PMID 35087996, 2020).
rectal tumor (2 papers, 2018 to 2019). "In multivariate analysis, both postulated deleterious PTPRT/PTPRD alterations and rectal tumors were independent factors associated with shorter PFS (HR, 3.33; 95% CI, 1.47–7.54; p = 0.0038 and HR, 2.56; 95% CI, 1.23–5.32; p = 0.0118, respectively)." (PMID 30200630, 2018). "We have previously shown that when considering clinical factors and PTPRT and PTPRD deleterious alterations, rectal tumors and PTPRT and PTPRD deleterious alterations were independent predictors of short PFS." (PMID 31366114, 2019).
uterine corpus endometrial carcinoma (2 papers, 2022). A endometrial carcinoma (disease) that involves the body of uterus. "Several PTPs, like PTPRT, PTPRB, and PTPRD, demonstrated a high mutation rate in skin cutaneous melanoma (SKCM) and uterine corpus endometrial carcinoma (UCEC) compared with other cancers due to the higher global mutation burden in the two cancer types." (PMID 36341348, 2022).
autism spectrum disorder (1 paper, 2017). A spectrum of developmental disorders that includes autism, and Asperger syndrome. "PTPRT was identified as a potential candidate gene for autism spectrum disorders (ASDs)." (PMID 28796977, 2017).
breast tumor (1 paper, 2021). "Meanwhile, breast tumor with high PTPRT was associated with low proliferation rate (measured by Ki67) and high apoptotic rates (measured by BCL-2)." (PMID 34414233, 2021).
colorectal tumors (1 paper, 2015). "The top ranked genes, PTPRT and CSMD1, which are unique to 1CT7 and A1309 cells, respectively, have previously been reported to be mutated in colorectal tumors." (PMID 25923178, 2015).
developmental delay (1 paper, 2021). "We then examined SCG2 expression in a PTPRT−/− null mouse model of developmental delay." (PMID 34815513, 2021).
lymph node metastases (1 paper, 2021). "Those patients with lymph node metastases were of lower PTPRT levels (p < 0.0001, 7474 patients)." (PMID 34414233, 2021).
malaria (1 paper, 2021). Malaria is a serious and sometimes fatal disease caused by a parasite that commonly infects a certain type of mosquito which feeds on humans. "PTPRT is a tyrosine phosphatase receptor involved in STAT3 pathway and was recently reported to be associated with mild malaria susceptibility in Benin populations." (PMID 34868193, 2021). "Genes with top scores encode for different malaria relevant functions such as regulation of inflammation (CSMD1), neural adhesion (CNTN4, PCSK5, CDH13, TMEM132), vascular epithelial development (FLT4), and protein kinases (PTPRT, PRKG1)." (PMID 34868193, 2021).
Mycobacterium infection (1 paper, 2025). Infections with bacteria of the genus Mycobacterium. "Additionally, we found a deletion in the intron of the PTPRT gene, which is linked to resistance against Mycobacterium infections." (PMID 40508044, 2025).
ovarian carcinoma (1 paper, 2017). A malignant neoplasm originating from the surface ovarian epithelium. "Interestingly, SNVs in PTEN (p.Cys124Ser and p.Ala126Thr) and PTPRT (p.Val1429Met), and one-base indels in RAF1 (p.Met350fs) and ARID1A (p.Arg1053fs) were shared by the endometrial and ovarian carcinomas but not found in the lung metastasis." (PMID 28103826, 2017).
ovarian clear cell cancer (1 paper, 2014). An invasive malignant neoplasm that arises from the ovary and is characterized by a predominance of clear and hobnail malignant epithelial cells. "Gain of copy number involving the PTPRT gene has been identified in a previous study on ovarian clear cell carcinoma by using array CGH." (PMID 24694993, 2014).
polycythemia (1 paper, 2019). Abnormally high mass or concentration of red blood cells in the blood, either due to an increase in erythropoiesis or a decrease in plasma volume. "The three characteristics appeared to be strongly correlated and supports the hypothesis that HCK amplification on the background of PTPRT depletion had directly resulted in aberrant bone marrow erythroid development, which subsequently led to the establishment of polycythemia and splenomegaly." (PMID 31065022, 2019). "To summarize, the combination of HCK overexpression and PTPRT loss was associated with some myeloproliferative characteristics such as hyperproliferation and STAT3 upregulation in vitro, and aberrant bone marrow erythroid maturation, polycythemia and splenomegaly in vivo." (PMID 31065022, 2019).
Splenomegaly (1 paper, 2019). Abnormal increased size of the spleen. "One out of three recipients of PTPRT−/− HSCs transduced with either HCK or MIGR1 control developed splenomegaly." (PMID 31065022, 2019).